HPSE (heparanase)
Diseases named in the same sentence as HPSE in open-access papers (continued):
Sharing a sentence is not in itself a finding about the gene and the disease.
breast carcinoma (continued). "Heparanase activity was significantly higher in malignant breast cancer cells than in MCF10AT cells and increased in MCF10AT cells after transfection with CXCL7." (PMID 35837284, 2022). "In a previous study, augmented SOD activity was related to the diminished expression and activity of heparanase, resulting in decreased invasion ability in breast cancer cells; thus, our experimental model confirms such findings." (PMID 35630523, 2022). "The addition of exogenous recombinant heparanase to MDA-MB-231 breast cancer cells also induces exosome secretion." (PMID 36358833, 2022). "HPSE was previously reported to promote tumor growth and metastasis in breast cancer by modulating phosphorylation of AKT, STAT5, and SRC." (PMID 36130926, 2022). "We previously reported that tGLI1 modulates the invasion of glioblastomas and breast cancer through the upregulation of heparanase and MMP9 expression, respectively." (PMID 36077791, 2022). "first revealed that upregulated miR-1258 inhibited breast cancer brain metastasis through targeting HPSE by using regulatory experiments, functional experiments, and clinical specimens’ validation." (PMID 36249037, 2022). "We assessed the correlation of HPSE expression with immune infiltration levels in bladder and breast cancers by the TIMER database." (PMID 34461608, 2021). "Overexpression of SOD3 inhibited breast carcinoma cell growth and invasion through reduced expression of heparanase." (PMID 33717151, 2021). "We used publically available microarray data sets comprising over 10,000 breast cancer patients to build a pooled set of gene-expression profiles with available outcome data in order to delineate the clinical relevance of heparanase in breast cancer." (PMID 34050190, 2021). "In vitro experiments showed that heparanase promoted tumor progression and increased cell viability via epithelial–mesenchymal transition, stemness, and anti-apoptosis pathways in luminal breast cancer." (PMID 34050190, 2021). "Heparanase is a key component of the breast tumor microenvironment and it was shown to be involved in primary breast cancer progression by creating a microenvironment that supports tumor growth, angiogenesis, and survival." (PMID 34050190, 2021). "We assume that the different molecular mechanisms of chemoresistance, which were found to be induced by heparanase, contribute synergistically to its involvement in breast cancer survival following drug therapy." (PMID 34050190, 2021). "In the current study, our data sample comprised over 10,000 breast cancer patients in whom heparanase expression was determined uniformly by microarray." (PMID 34050190, 2021). "The results of the present study suggest that heparanase has a role in increased cell viability following chemotherapy in ER+ breast cancer cells." (PMID 34050190, 2021). "Groult and colleagues have tested red seaweed carrageenan regarding its anti-heparanase effect on MDA-MB-231 breast cancer cells." (PMID 34349175, 2021). "The information, which accumulated in the literature about the impact of heparanase on breast cancer chemoresistance, is limited." (PMID 34050190, 2021). "In metastatic breast cancer cells, the miRNA miR-1258 was found to suppress heparanase expression and subsequently control tumor invasion and metastasis." (PMID 34681753, 2021). "Analysis of HPSE expression and cancer prognosis using the Kaplan–Meier plotter database showed that high HPSE expression was related to poor RFS, DMFS, PPS, and OS rates in breast cancer; it was also associated with poor PPS and OS rates in stomach cancer." (PMID 34461608, 2021). "For example, NET1e regulates the expression of oncogene neuroepithelial cell transforming 1 (NET1) in breast cancer to promote tumorigenesis, while HPSEe regulates the expression of heparanase (HPSE) to promote cancer invasion and metastasis." (PMID 33119754, 2021).
breast carcinoma (continued). "λ-CO also downregulated additional factors linked with ECM remodelling and breast cancer progression, in particular MT1-MMP and its direct target MMP-2, and our data suggest that HPSE protein level acts as an orchestrator of MMP-2 activation." (PMID 34677445, 2021). "Estrogen in breast cancer cells increases heparanase expression, and treatment of cholangiocarcinoma cells (bile duct cancer) with the estrogenic inducer 17β-estradiol upregulated heparanase mRNA." (PMID 34681753, 2021). "Heparanase has also been identified in the nucleus of human glioma and breast cancer cell lines and in patient samples of squamous cell carcinoma and adenocarcinoma." (PMID 34681753, 2021). "In the current study, we noted that the higher pre-treatment heparanase concentration is a good indicator for invasive phenotypes of breast cancer and shorter post-operative survival times." (PMID 34070058, 2021). "Transwell cell migration and invasion assays showed that overexpression of CDYL2b in MDA-MB-231 and Hs578T cells suppressed breast cancer migration and invasion, which was partially rescued by expressing HPSE, HLA-F, and SELL in these cells." (PMID 32373210, 2020). "We noticed that overexpression of heparanase in T47D breast carcinoma cells resulted in more dispersed cell colonies (left)." (PMID 32038981, 2020). "Heparanase overexpression dramatically increases exosome secretion in human cancer cells of myeloma, lymphoblastoid, and breast cancer." (PMID 31963505, 2020). "Although miR-1258 has already been reported to act as a tumor suppressor by targeting heparanase in nonsmall cell lung cancer, breast cancer, and gastric cancer, its function in CRC is unclear." (PMID 31717435, 2019). "In glioma and breast carcinoma, this was found to be about 7% of the cytosolic enzyme, and nuclear heparanase was enzymatically active, degrading nuclear HS." (PMID 31850210, 2019). "Heparanase-specific and reactive CD8+ T cells were identified in the bone marrow of a sample of breast cancer patients, and were functionally reactive to heparanase-overexpressing tumor cells." (PMID 31110966, 2019). "Specimens from breast cancer patients showed that lymphocytes express heparanase and when serum collected from these patients was introduced to fresh lymphocytes, heparanase expression was stimulated in the normal lymphocytes." (PMID 32010611, 2019). "It was also observed that recombinant heparanase stimulated exosome secretion from breast carcinoma cells." (PMID 30922347, 2019). "Of the 121 biopsies of primary breast carcinoma, 51 exhibited strong staining of heparanase (+2), of which 22 (43%) were diagnosed later with metastatic disease." (PMID 29464068, 2018). "Taken together, the results clearly show that heparanase is critically important for the progression of stage I breast cancer." (PMID 29464068, 2018). "The role of heparanase in breast cancer has been extensively examined in preclinical studies, but clinical evidence is limited." (PMID 29464068, 2018). "Here, we examined the expression of heparanase in pairs of primary and the resulting distant metastases of breast carcinoma." (PMID 29464068, 2018). "In order to examine the expression of heparanase in primary tumors vs metastases, we collected specimens from 121 breast carcinomas." (PMID 29464068, 2018). "In agreement with clinical observations, in vitro heparanase enzyme augmented INSR signaling / downstream AKT activation in breast carcinoma cell lines, and enhanced insulin-induced growth of breast tumor cells." (PMID 28038446, 2017). "Down-regulation of heparanase expression in response to PG545 was noted in 4T1 breast carcinoma model." (PMID 28388547, 2017). "Preferential expression and involvement of heparanase in breast cancer are particularly well documented, both in experimental and clinical settings." (PMID 28038446, 2017).
breast carcinoma (continued). "Altogether these results demonstrate that INSR signaling in breast carcinoma cells is enhanced in the presence of heparanase and results in accelerated cell proliferation." (PMID 28038446, 2017). "HPSE expression was elevated in breast cancer specimens compared to normal specimens (OR = 34.47, 95% CI = 4.90 – 242.30, P = 0.0004), and the inter-study heterogeneity was relatively small (P = 0.14)." (PMID 28388549, 2017). "ER status is correlated with HPSE expression, and experiments have confirmed that HPSE acts downstream of ER signaling to promote breast cancer progression." (PMID 28388549, 2017). "Although more large-sample clinical data is needed to validate our findings, the results of this study suggest that the use of HPSE as a predictive factor for clinical prognosis and as a treatment target would benefit breast cancer patients." (PMID 28388549, 2017). "HPSE expression was similarly elevated in breast cancer tissue compared to benign breast tumor tissue (OR = 23.51, 95% CI = 2.40 – 230.28, P = 0.007)." (PMID 28388549, 2017). "While our findings reveal augmented insulin receptor signaling in the presence of heparanase in breast carcinoma, a limitation of our study is that precise molecular mechanism underlying this phenomenon has not been determined." (PMID 28038446, 2017). "Looking at the biological functions of CCNE2, HPSE, and PFKM proteins, they are for the most part, involved in cell cycle G1/S transition, proliferation and carcinogenesis, and associated with breast cancer." (PMID 28505145, 2017). "We demonstrate that heparanase activity leads to enhanced insulin signaling and activation of downstream tumor-promoting pathways in breast carcinoma cells." (PMID 28038446, 2017). "Previous studies have showed that miR-1258 expression is attenuated in human breast cancer cells and patient tissues, and miR-1258 suppresses breast cancer brain metastasis by targeting heparanase (HSPE)." (PMID 27270326, 2016). "Nevertheless, laboratory studies now implicate heparanase in an invasive cell phenotype driven by the small GTPases: Rac1 and RhoA in brain metastatic breast cancer cells." (PMID 25105093, 2014). "For example, elevated heparanase expression was associated with the lymph node status, late clinical stages, a short overall survival, and a short relapse-free survival with the highest heparanase levels in breast cancer those with lymph node metastasis." (PMID 25105093, 2014). "Further study using proper methods, such as chromatin immunoprecipitation assay (CHIP), to confirm these potential transcription factors specific binding to heparanase promoter in breast carcinoma is worth to be warranted." (PMID 24632672, 2014). "Collectively, these results demonstrate that DNA methylation play the regulation role in heparanase gene in different stages of breast cancer and present a direct effect on tumor progression." (PMID 24632672, 2014). "TD4-143-1, which is a selectively sulfated tetrasaccharide containing unsubstituted glucosamine residues, which inhibited heparanase activity and suppressed invasion of breast cancer cells in vitro." (PMID 25105093, 2014). "We detected levels of heparanase expression and DNA methylation patterns of its promoter in breast cancer cell lines (MCF-7 and MDA-MB-435) and clinical tissues, respectively." (PMID 24632672, 2014). "By MSP detection, the methylation of heparanase was identified in 41.3% of late breast cancers (Stage IV), 80.8% of early breast cancers (Stage I) and 90.0% of control samples." (PMID 24632672, 2014). "In this study, we also revealed heparanase was more frequently methylated in breast cancer samples at early stage than in those at late stage." (PMID 24632672, 2014). "In breast cancer samples, the correlations between DNA methylation of heparanase and several clinicopathological parameters were further investigated." (PMID 24632672, 2014).
breast carcinoma (continued). "The aim of this study is to determine the differential regulation of heparanase gene expression in specific stages of breast cancer by DNA methylation." (PMID 24632672, 2014). "Correlation of clinicopathological factors with the methylation status of the heparanase gene in breast cancer samples." (PMID 24632672, 2014). "We will describe recent findings on the function of HSPGs and heparanase in breast cancer behavior and progression." (PMID 23984412, 2013). "Heparanase seems to be related to several aspects regulating the potential of breast cancer metastasis." (PMID 23984412, 2013). "Altogether, these data point to heparanase as a good target molecule to break breast cancer progression." (PMID 23984412, 2013). "It has been recently reported that heparanase expression and activity in brain metastatic breast cancer cell (MDA-MB-231) can be inhibited by the microRNA miR-1258." (PMID 23984412, 2013). "Several lines of evidence indicate that heparanase is upregulated in all human sarcomas and carcinomas and occurs at elevated levels in body fluids of breast cancer patients." (PMID 23984412, 2013). "Heparanase seems to be related to several aspects that regulate the potential of breast cancer metastasis." (PMID 23984412, 2013). "Heparanase is considered a critical molecular determinant of brain metastasis in melanoma and breast cancer, but surprisingly high exogenous heparanase concentrations were shown to downregulate invasion of brain metastatic melanoma cells." (PMID 23344048, 2013). "In support of the role of HPSE in promoting B-Met is a recent study that reported miR-1258 to be a suppressor of breast cancer B-Met through the direct targeting of HPSE." (PMID 23750336, 2013). "According to this idea, it was shown that miR-1258 and heparanase levels are inversely correlated in breast carcinoma." (PMID 23984412, 2013). "Interactions of the breast cancer cells with integrins, fibronectin, tenascin C, laminins, collagens, endoglin, hyaluronan, heparanase and proteoglycans can contribute to the metastatic process." (PMID 23343205, 2013). "The importance of these data was confirmed by breast cancer tissue array, which demonstrates a correlation between estrogen receptor (ER) and heparanase expression." (PMID 23984412, 2013). "It has been shown that breast cancer cells from brain metastatic sites exhibited high levels of heparanase, compared to parental cells." (PMID 23984412, 2013). "Taking into account the involvement of heparanase in breast cancer, several heparanase inhibitors have been developed in order to affect tumor growth and bulk angiogenesis." (PMID 23984412, 2013). "COX-2 localization in breast cancer specimens was similar to heparanase and there is a correlation between heparanase and COX-2 expression, which is evident in invasive breast cancer." (PMID 23984412, 2013). "Heparanase expressed by breast cancer cells participates in angiogenesis and neovascularisation by degrading the polysaccharide scaffold of the endothelial BM, thereby releasing angiogenic growth factors from the ECM." (PMID 23343205, 2013). "It was demonstrated that VEGF is upregulated in MDA-MB-435 human breast carcinoma cells overexpressing heparanase." (PMID 23984412, 2013). "DNA topoisomerase I, a key player during DNA replication, is regulated by nuclear heparanase, thus affecting cell proliferation of breast cancer cells in brain metastases." (PMID 23984412, 2013). "In this review, we will describe recent findings on the function of HSPGs and heparanase in breast cancer behavior and progression." (PMID 23984412, 2013). "One related to brain metastasis is the recent report of EGF promoting heparanase function and Topoisomerase I localization in brain metastasizing breast cancer cells." (PMID 23217186, 2012).
breast carcinoma (continued). "A tumor-inducing effect on heparanase expression by lymphocytes of breast cancer patients was found to be decreased in breast cancer patients rendered free of tumor by surgery or treated with tamoxifen." (PMID 23300607, 2012). "When CD44, HA, and heparanase are highly expressed in breast cancer cells, they generate a microenvironment that facilitates tumor progression and invasion." (PMID 21749678, 2011). "Understanding of the combined effects of heparanase, syndecan-1, and IL-8 on breast cancer progression, development of bone metastases, and activation of bone resorption is currently the focus of intense investigation in our laboratory." (PMID 20200931, 2010). "We previously demonstrated that breast cancer cells expressing high levels of heparanase exhibit enhanced shedding of the syndecan-1 proteoglycan." (PMID 20200931, 2010). "Further investigation of the role of the heparanase–shed syndecan-1 axis in breast cancer progression should focus on disruption of heparanase function, which is likely to profoundly affect tumor growth, metastasis, and osteolysis." (PMID 20200931, 2010). "Further investigation of the role of this important axis in breast cancer progression should focus on disruption of heparanase function, which is likely to profoundly affect tumor growth, metastasis, and osteolysis." (PMID 20200931, 2010). "Recently, expression of VEGF-C was shown to be induced by heparanase in prostate cancer cells, epidermoid cancer cells, breast cancer cells, and melanoma." (PMID 20652010, 2010). "In this study, conditioned medium from breast cancer cells expressing high levels of heparanase was shown to significantly stimulate human osteoclastogenesis in vitro (p < .05)." (PMID 20200931, 2010). "Co-regulation of heparanase and MMPs was also noted by a marked decrease in MMP (primarily MMP-2,-9 and 14) expression following transfection and over-expression of the heparanase gene in cultured human mammary carcinoma (MDA-MB-231) cells." (PMID 19360105, 2009). "Interestingly, knockdown (KD) of BPTF in breast cancer cells leads to a reduction in heparanase (HPSE) expression, thereby compromising HPSE’s ability to cleave heparan sulfate proteoglycans (HSPGs), which serve as NCR ligands on the surface of tumor cells." (PMID 39935175, 2025). "Furthermore, inhibition of heparanase expression in breast cancer cells via knockdown of the bromodomain PHD finger transcription factor (BPTF), a known activator of heparanase expression, enhanced antitumor NK cell-mediated cytolytic activity in the TME." (PMID 40519272, 2025). "Importantly, the antibody attenuated tumor growth and metastasis (myeloma, glioma, pancreatic cancer, breast carcinoma, all expressing heparanase enzymatic activity) in both immunocompetent (syngeneic) and immunocompromised mouse models." (PMID 40940793, 2025). "Collectively, these observations may have implications in the clinical setting of breast cancer and therapy using HPSE inhibitors." (PMID 37297024, 2023). "In support of HPSE-mediated breast cancer metastasis, miR-1258 levels were shown to inversely correlate with HPSE expression and activity and the overall metastatic potential of breast cancer cells." (PMID 37297024, 2023). "Here, we utilised the well-defined MMTV-PyMT mouse model of spontaneous mammary tumour development to define the precise role of HPSE in murine breast cancer progression, which may in turn complement our understanding of the human malignancy." (PMID 37297024, 2023). "Future studies focusing on the role of HPSE in mediating mammary tumour metastasis in MMTV-PyMT transgenic mice may benefit from using animals generated on an FVB background." (PMID 37297024, 2023). "However, the complete mechanism(s) exerted by heparanase to promote cancer progression is still incompletely understood in the context of breast cancer tumors." (PMID 34050190, 2021).